Y_RNA (Y RNA )
Gene: Miscellaneous RNA gene on chromosome 9 (33,830,978 to 33,831,078, forward strand). Ensembl gene ENSG00000200834.
Homologues: Orthologues: chimpanzee Y_RNA (99% identical), macaque Y_RNA (92% identical). Paralogues in human: Y_RNA (85% identical), RNY3 (84% identical), Y_RNA (84% identical), Y_RNA (83% identical), Y_RNA (82% identical), RNY3P1 (81% identical), Y_RNA (81% identical), Y_RNA (80% identical), RNY3P14 (79% identical), RNY3P3 (79% identical), Y_RNA (79% identical), RNY3P11 (78% identical), and 92 more.